TNF (tumor necrosis factor)
Diseases named in the same sentence as TNF in open-access papers (continued):
Sharing a sentence is not in itself a finding about the gene and the disease.
Obesity (continued). "Obesity promotes the secretion of large amounts of TNF-a by adipocytes and macrophages in the PVAT, and TNF-a promotes aortic intimal-medial thickening." (PMID 37822930, 2023). "Specific inflammatory cytokines are produced in response to increased fat stores during obesity [interleukin-6 (IL-6) and TNF]." (PMID 37534085, 2023). "One indication of the possible important function of TNF-α in regulating obesity-related IR was that a reduction in body weight after dietary treatment resulted not only in improved IS, but also in lower TNF-α-mRNA expression levels." (PMID 37239098, 2023). "Chronic inflammation can be triggered by the metabolic imbalance resulting from obesity, since immune cells are stimulated to increase the production of some cytokines, such as tumor necrosis factor-α (TNF-α)." (PMID 37444314, 2023). "The cytokines IL-6, TNF-α, and leptin play critical roles in the development of obesity, insulin resistance, and chronic inflammation, which culminate into obesity-related metS." (PMID 36982743, 2023). "To determine how the expressions of the circRNAs were changed by obesity in the brain, we chose seven obesity-related blood serum factors, glucose, insulin, TNF-α, IL-6, PA, LA, and Chol, that mimic obesity in the brain." (PMID 37047207, 2023). "TNF‐α is overexpressed in the fat tissue (adipose) and muscle of both obese humans and rodent obesity models." (PMID 38107091, 2023). "Tumour necrosis factor α (TNF-α), the most extensively studied cytokine, plays a crucial role in the modulation of insulin resistance seen in obesity and T2D." (PMID 36838411, 2023). "Overall, previous studies presented an overexpression of TNF-α levels in rodents and humans suffering from obesity." (PMID 37239098, 2023). "They employed a high-fat diet-induced murine model of obesity and discovered a significant increase in TNF-α and Ccl2 mRNA levels in obese mice, which were tightly correlated with the histone H3 acetylation augmentation." (PMID 37862340, 2023). "Obesity predisposes individuals to a proinflammatory state via the increased secretion of inflammatory mediators, particularly IL-6, MCP-1, and TNF-α, from adipose tissue." (PMID 36717684, 2023). "The basic reason for IR in obesity lies in the products released from adipose tissue which include free fatty acids and inflammatory mediators such as TNF alpha." (PMID 36911845, 2023). "Obesity is related to the increase of circulating Tumor Necrosis Factor (TNF, TNF-α), a pro-inflammatory cytokine that induces the death of liver cells." (PMID 36866057, 2023). "Obesity results in the elevated circulating levels of pro-inflammatory cytokines such as TNFα which can directly affect muscle protein synthesis and mitochondrial activity." (PMID 36875847, 2023). "The key importance of TNF signalling in obesity-induced inflammation and metabolic complications was vastly demonstrated in animal models and also in humans." (PMID 36175539, 2023). "The expression of adiponectin by adipocytes is decreased in individuals with obesity, while it is also inhibited by pro-inflammatory cytokines, such as TNF and IL-6, as well as conditions such as hypoxia and oxidative stress." (PMID 37755259, 2023). "In future studies it would be interesting to address if low adipose tissue SIK2 expression in obesity and insulin resistance is indeed a result of low-grade inflammation and the presence of elevated TNFα." (PMID 37386070, 2023). "Macrophages and their production of TNF-α, in particular, contribute to atrophy (ie, sarcopenic obesity) seen in many cases of obesity." (PMID 37492183, 2023). "Leptin and TNF-α are positively correlated with body obesity and contribute to promoting inflammation and IR development." (PMID 36991247, 2023). "TNFα is a pro-inflammatory cytokine and the first “adipokine” identified to be secreted by adipose tissue, and plays a key role in obesity-related metabolic disorders." (PMID 37764703, 2023).
Obesity (continued). "According to previous studies, polyunsaturated fatty acids decrease sVCAM-1 and TNF-α in people living with obesity." (PMID 38024342, 2023). "TNF is an important mediator of insulin resistance in obesity and diabetes, through its capacity to diminish the tyrosine kinase activity of the insulin receptor, resulting in higher levels of inflammation." (PMID 37275644, 2023). "Early studies suggested that obesity can induce production of proinflammatory cytokines such as tumor necrosis factor (TNF-a) in adipose tissue, leading to inflammatory response in patients with sepsis." (PMID 37205044, 2023). "TNF-α is a therapeutic target for inflammatory illnesses such as rheumatoid arthritis, Crohn’s disease, atherosclerosis, sepsis, and obesity." (PMID 37432262, 2023). "Obesity is related to an increased production of cytokines for the pro-inflammatory response (e.g., leptin, TNF-α, and IL-6) and a decreased secretion of adipokines that protect inflammatory response (e.g., adiponectin and IL-10)." (PMID 37821991, 2023). "TNF-alpha is one of the earliest markers of obesity and T2D, and its raised levels represent a major contributing factor to the development and maintenance of insulin resistance." (PMID 37510186, 2023). "Increasing serum levels of pro-inflammatory cytokines (IL-1, IL-6, and TNF-a) and acute phase proteins in obesity, especially abdominal obesity, are important mediators in bone resorption and osteoclast differentiation." (PMID 37705033, 2023). "Inflammatory pathways, including NF-κB signaling, are aggravated in adipose tissues affected by obesity, resulting in the elevated expression of subsequent cytokines such as TNFα, IL6, IL1β, and others." (PMID 37764703, 2023). "In obesity, various adipocyte-derived pro-inflammatory cytokines, including TNF-α, interleukin-1β, interleukin-6, monocyte chemotactic protein-1, leptin, and resistin are overproduced, contributing to IR." (PMID 37503477, 2023). "Obesity and particularly elevated levels of ROS, TNF-α, IL-6, and visfatin down-regulate the secretion of adiponectin." (PMID 37372025, 2023). "Reductions in TNF α and IL-6 levels were also observed in a group of patients with severe obesity undergoing bariatric surgery." (PMID 38276294, 2023). "Previous studies have demonstrated that obesity is correlated with the enhanced secretion of inflammatory cytokines, including IL-6, IL-1β, and TNF-α." (PMID 38035300, 2023). "TNF-alpha and IL-6 are pro-inflammatory cytokines that can be produced by adipose tissue in response to obesity-related stress." (PMID 37629396, 2023). "For example, during the early stages of HFD-induced obesity, MMe macrophages increased adipose tissue inflammation by upregulating inflammatory markers such as TNF-α, IL-6, and IL-1β, as well as genes involved in lipid metabolism." (PMID 37153549, 2023). "Obesity and overweight are identified as risk factors for flare in patients with SLE, by the expression of inflammatory cytokines such as tumor necrosis factor-alpha (TNF-α) and interleukin 6 (IL-6)." (PMID 37384711, 2023). "The PERK pathway during excessive ER stress also activates cytokines such as TNF-a, IL-6, and IL-1β, a major contributor to the inflammation that induces obesity." (PMID 38140341, 2023). "TNF-α, primarily secreted by adipose tissue, exhibits elevated gene and protein expression in the presence of obesity, whereas only 30% of IL-6 production originates from adipose tissue." (PMID 37919772, 2023). "In obesity, adipose tissues produce proinflammatory cytokines such as interleukin‐6 (IL‐6) and tumor necrosis factor‐α (TNF‐α), and thus obesity is regarded as a chronic systemic inflammatory disease." (PMID 37773696, 2023). "TNF-α also plays a vital role in the pathogenesis and development of obesity-induced insulin resistance as demonstrated by the augmented levels of TNF-α in systemic circulation, liver, and adipocytes." (PMID 37215099, 2023).
Obesity (continued). "Adiponectin, leptin, IL-6, TNF-α and MCP-1 plasma levels were measured by enzyme-linked immuno assays for 60 subjects with FPLD2 and for 60 subjects with obesity." (PMID 37081489, 2023). "Among these, 3 genes - AKT1, IL-6, and TNF - were shared between the obesity and gastric cancer sets." (PMID 37954072, 2023). "Obesity always comes with higher levels of inflammatory factors, such as tumor necrosis factor-α (TNF-α) and interleukin-6 (IL-6)." (PMID 36777345, 2023). "Considerable researches have proved that PQQ has a positive effect on inflammatory diseases such as obesity, diabetes, and sepsis via the mediation of pro-inflammatory cytokine such as IL-6, IL-1β and TNF-α." (PMID 37935689, 2023). "Individuals with obesity were found to have upregulated adipose and systemic TNF-α expression, together with increased plasma levels of hs-CRP, MDA, and OX-LDL, all of which were positively associated with BMI." (PMID 37894865, 2023). "The number of CLS is strongly correlated with the expression of inflammatory cytokines like TNF-α, indicating that infiltrating macrophages have a pro-inflammatory effect on adipose tissue in obesity." (PMID 37153549, 2023). "Individuals with obesity displayed increased adipose TNF-α gene/protein expression as well as elevated plasma levels of TNF-α, CRP, MDA, and OX-LDL (p ≤ 0.05)." (PMID 37894865, 2023). "Progranulin levels are known to increase in obesity and have been demonstrated to mediate TNF induced increases in the proinflammatory cytokine IL-6 and insulin resistance." (PMID 38057339, 2023). "TNF-α signalling can alter a broad range of metabolic pathways and affect insulin sensitivity in obesity." (PMID 37033938, 2023). "During obesity, macrophages infiltrate and produce cytokines such as tumor necrosis factor-alpha (TNF-α), interleukin 1 beta (IL-1β), IL-18, IL-6, and interferon-gamma (IFN-γ)." (PMID 37214340, 2023). "The inflammatory marker tumor necrosis factor-alpha (TNF-α) has been found to increase insulin resistance in diabetic patients, and other inflammatory markers also exacerbate both obesity and type 2 diabetes." (PMID 37916232, 2023). "Clinical studies have shown that individuals with obesity have increased levels of TNF-α in their sera and that these levels decrease with weight loss." (PMID 36766750, 2023). "Diet-induced obesity increases the activation of inflammation in the mediobasal hypothalamus, resulting in the production of proinflammatory cytokines (TNF-α, IL-1β, and IL-6) and impairment in insulin and leptin signaling." (PMID 36677011, 2023). "Obesity, diabetes mellitus, and metabolic syndrome are diseases mediated by proinflammatory cytokines such as TNF-α, IL-1β, and IL-6." (PMID 37685515, 2023). "Second, TNF-α released from tumor and stromal cells acts as a critical inflammatory factor in the obesity-induced microenvironment." (PMID 36593475, 2023). "Fifth, since TNF-α and IL-6 are also produced by macrophages in the adipose tissue and muscle, information, such as obesity and physical activity in SZ patients should be included when the patient enters the hospital." (PMID 37937262, 2023). "Other circulating factors released in obesity, such as IL-6 and TNF-α, further increase BBB permeability." (PMID 37086380, 2023). "Systemic low-grade inflammation is a cornerstone in the relationship between obesity and carcinogenesis, a relationship best described by the actions of released adipokines (studied here), interleukin 6 (IL-6) and Tumor Necrosis Factor α (TNF-α)." (PMID 36900364, 2023). "Another study found a positive correlation of TNF-α and IL-12, pro-inflammatory cytokines with BMI and obesity in patients with type 1 diabetes." (PMID 37180128, 2023). "Upregulation of TNF-α and IL-6 promoted hepatic steatosis and inflammation in a mouse obesity model." (PMID 38313077, 2023).
Obesity (continued). "MCP-1 is stimulated by the presence of IL-1β, TNF-α, IL-8, IL-4, and IL-6, and thus further aids in the macrophage recruitment to adipose tissue seen in obesity." (PMID 37571308, 2023). "In obesity, increased levels of TNFα are observed, and TNFα levels correlate with the extent of adiposity and associated insulin resistance." (PMID 37958808, 2023). "At time 0, the level of transcription (mRNA) of all genes analyzed were higher in the group with obesity compared with the control group, ranging between 3.5-times of TNF-α and 18.7-times of IL-4." (PMID 37215211, 2023). "Here, we expanded this observation to different anatomical sites and investigated the effects of obesity and joint loading on the metabolic prolife of SFs from different joints and how they respond to inflammatory TNFα stimuli." (PMID 37006170, 2023). "TNF-α has a key role in the inflammatory process among other obesity-related metabolic disturbances." (PMID 38202671, 2023). "Excessive dietary intake of SFA is usually associated with increased obesity-related hepatic inflammatory plasma markers such as ALT and AST, as well as cytokines, such as TNFα and IL-1β, involved in the inflammatory response." (PMID 38004155, 2023). "The implications of this chronic TNF elevation in adipose tissue during obesity have been studied in vitro through the addition of soluble TNF to the tissue’s cellular constituents, including adipocytes, preadipocytes, and endothelial cells." (PMID 36766750, 2023). "Pregnant women with obesity and diabetes often have an increase in pro-inflammatory cytokines and adipokines, such as TNF-α, IL-6, IL-1β, leptin, and resistin, which are involved in the inflammatory response." (PMID 37515062, 2023). "It is widely acknowledged that TNF-α expression increases in cases of obesity and plays a major role in the inflammatory pathogenesis of NASH23." (PMID 37468618, 2023). "Several previous reports have documented that obesity decreases the response rate to anti-TNF-α agents in RA." (PMID 38813042, 2023). "Obesity-induced inflammatory cytokines, particularly tumor necrosis factor-α (TNF-α), also impair insulin signaling via the serine phosphorylation of IRS-1." (PMID 36671511, 2023). "Smooth muscle myocytes secrete many cytokines and other molecules, such as IL-6, TNF-α, and myonectin, related to the inflammatory process and can become inflamed in obesity, leading to increased muscle inflammation." (PMID 37492183, 2023). "Adipose tissue autophagy flux is augmented by obesity-induced inflammatory cytokines, particularly TNF-α, via upregulating autophagic genes." (PMID 37534085, 2023). "The aim of this study was to evaluate the effect of serum selenium on PPAR-γ and the selected proinflammatory cytokines (IL-1β, IL-6, TNF-α) in relation to depressive symptoms and obesity in middle-aged women." (PMID 37049434, 2023). "Previous studies also found increased levels of TNF-α and IL-10 in serum or liver tissue in obesity-related NAFLD rat and mouse models established by high-fat diet or monosodium glutamate (MSG) injection." (PMID 37174318, 2023). "The pro-inflammatory ATMs are one of the key cell types responsible to produce pro-inflammatory cytokines such as TNF-α, IL-1β, and IL-6, which contribute to obesity-related adipose tissue inflammation." (PMID 37153549, 2023). "In obesity, multiple adipokines such as TNF-α regulate adipocyte homeostasis, disturb the IGF-1 synthesis, and impair its signaling." (PMID 36991247, 2023). "Tumor necrosis factor α (TNFα) was elevated in obesity and is involved in the induction of MMP-9 in monocytic cells." (PMID 37658104, 2023). "This indicates the presence of the obesity-related latent inflammatory process in the patients with high BMI and further promotes the production of inflammatory cytokines like TNF-α, interleukins-6 (IL-6), and IL-1 in adipose tissue." (PMID 36819139, 2023).
Obesity (continued). "On top of that, comparing TNF-α and IL-6, the level of TNF-α has been consistently higher in severe COVID-19 patients and those who suffer from comorbidities such as obesity, hypertension, and chronic heart failure." (PMID 37047115, 2023). "In individuals with obesity, IL-6 and TNF-α have more secretion in the morning instead of the night and are related to BMI and sleep disorder." (PMID 37275639, 2023). "Obesity is regarded as a kind of chronic inflammation and can increase the levels of TNFα, IL-1β, IL-6, and IL-18 within adipose tissue and systemically, such as through inflammasome activation in macrophages." (PMID 37526777, 2023). "Increased expression of TNFα has been observed in the adipose tissue of humans and mouse models of obesity and T2D." (PMID 37755259, 2023). "In contrast, adiponectin normally downregulates TNF-α expression in the liver, but its levels are low in obesity, thus TNF-α production is enhanced, with subsequent effects in the liver." (PMID 37407724, 2023). "Regarding metabolic syndrome, previous authors described how adipose tissues of patients with concomitant obesity and asthma disease produced cytokines, TNF-α, and interleukins, which also promoted systemic inflammatory response." (PMID 37920579, 2023). "For instance, supplementation with polysaccharides extracted from green walnut husk reduced the levels of pro‐inflammatory cytokines TNF‐α and IL‐1β, via gut microbiota regulation, which is helpful to inhibit the occurrence of obesity." (PMID 37823169, 2023). "Accordingly, the goal of this narrative review is to summarize the effects of TRE and ADF on body weight and key circulating inflammatory markers, i.e., CRP, TNF-alpha, and IL-6, in adults with overweight and obesity." (PMID 37139450, 2023). "Patients with obesity and type 2 diabetes showed significant reductions in TNF-α, IL-6, CRP, conjugated dienes, and MDA in addition to significant rises in GPx, SOD, and GSH after three months of a lifestyle intervention (diet and physical activity)." (PMID 37109709, 2023). "Obesity itself, as one of the main features of cardiometabolic syndrome, promotes the generation of pro-inflammatory factors, including TNF-α, in turn promoting insulin resistance." (PMID 36839268, 2023). "During obesity, adipose tissue secretes a large amount of proinflammatory adipokines such as tumor necrosis factor-α (TNF-α) and resistin, which induce insulin resistance and lead to metabolic disorders." (PMID 37383400, 2023). "Regarding obesity, it is known that the increase of adipose tissue involves changes in the molecular expression pattern of these cells, altering the secretion of TNF-α." (PMID 37427330, 2023). "MMP3 appears to contribute to the multiple molecular aspects of insulin resistance pathogenesis in obesity through inflammation since treatment with an MMP3 inhibitor abolished MMP3-mediated secretion of TNFα." (PMID 37445827, 2023). "The high abundance of Norank_f_Muribaculaceae is beneficial for reducing serum levels of TG, TC, LPS, and TNF-α, as well as improving obesity in general." (PMID 37048203, 2023). "The association between obesity and pulmonary diseases, including ILD, can be related to TNF-α -, MCP-1 -, and TGF-β1-dependent pathways, insulin resistance, or altered lung microbiota." (PMID 36836775, 2023). "Obesity and metabolic syndrome are pro-inflammatory states characterised by the release of inflammatory mediators such as interleukin 6 (IL-6) and TNF-α." (PMID 37233716, 2023). "Obesity is characterized by a persistent, low-grade inflammation that is fueled by adipocyte-released proinflammatory mediators such TNF-α, IL-1, and IL-6." (PMID 37734921, 2023). "The proinflammatory cytokines TNFα, IL1, and IL6 are locally increased in obesity, and cause PTP1B activation and insulin resistance." (PMID 37389126, 2023).